SPRY1 (sprouty RTK signaling antagonist 1)
Diseases named in the same sentence as SPRY1 in open-access papers (continued):
Sharing a sentence is not in itself a finding about the gene and the disease.
ovarian carcinoma (5 papers, 2012 to 2022). A malignant neoplasm originating from the surface ovarian epithelium. "Here, we report the inverse correlation between the expression of Spry1 and growth, proliferation, invasion and migration of ovarian cancer cells." (PMID 24932220, 2014). "Further investigation is underway to elucidate the role of Spry1 and other members of the Sprouty family in ovarian cancer and to evaluate practical value of this protein family in novel diagnostic, prognostic and therapeutic strategies." (PMID 24932220, 2014). "Our prior work showed that Spry1 is downregulated in the majority of the ovarian cancer cell lines studied." (PMID 24932220, 2014). "Using two cell lines with distinct Spry1 expression profiles, here we demonstrate how alterations in the protein expression impact functional properties of ovarian cancer cells." (PMID 24932220, 2014). "Since there clearly is a need for further investigation exploring the role of Spry1 in the context of ovarian cancer, we examined in the present study the correlation between the expression of Spry1 and the biological behavior of ovarian cancer cells." (PMID 24932220, 2014). "Our recent study on a panel of human ovarian cancer cells revealed that SKOV-3 cells barely express the Sprouty isoform 1 (Spry1) while 1A9 cells maintain it at a level similar to normal ovarian cells." (PMID 24932220, 2014). "To assess the effect of the Spry1 expression on ovarian cancer biology, we intended to examine viability of SKOV-3 cells after transfection with the plasmid encoding the full-length sequence of Spry1." (PMID 24932220, 2014). "Collectively, our study unveiled the differential expression of Spry1 and Spry2 proteins in various ovarian cancer cell lines." (PMID 23251157, 2012). "Our results also indicate the differential expression of Spry1 and/or Spry2 across the ovarian cancer cell lines studied." (PMID 23251157, 2012). "As an initial attempt, we aimed in this study to evaluate the expression pattern of Spry1 and Spry2 isoforms in a panel of human epithelial ovarian cancer cell lines." (PMID 23251157, 2012). "Initial studies were carried out to investigate the expression of Spry1 and Spry2 proteins in seven commonly-used human epithelial ovarian cancer cell lines by western blot analysis using Spry1 and Spry2 specific antibodies." (PMID 23251157, 2012). "In the present study we investigated the expression of Spry1 and Spry2 isoforms in a panel of human ovarian cancer cell lines in vitro." (PMID 23251157, 2012). "Our investigation unveiled the differential expression of Spry1 and Spry2 proteins in a range of human epithelial ovarian cancer cell lines." (PMID 23251157, 2012). "However, it has been reported that high expression of SPRY1 can reduce the proliferation, invasion and distant metastasis of ovarian cancer cells." (PMID 36035369, 2022). "The human ovarian cancer cell line 1A9 expresses the Spry1 protein." (PMID 24932220, 2014). "Taken together, our results highlight the role of Spry1 in ovarian cancer cell biology." (PMID 24932220, 2014). "In other words, the malignant phenotype of the ovarian cancer cell lines might be reflected in part by their ability to differentially express Spry1." (PMID 24932220, 2014). "Our results suggest that Spry1 may function as a negative regulator of vitality and survival and an inhibitor of motility and invasion in human ovarian cancer cell biology." (PMID 24932220, 2014). "Exploring mechanisms underlying anti-proliferative and anti-survival effects of the Spry1 transfection in ovarian cancer cells, we found that induced expression of Spry1 activates proapoptotic processes, with implication of Bcl-2 protein family and caspase pathways." (PMID 24932220, 2014). "We previously demonstrated that the human ovarian cancer cell line SKOV-3 barely expresses Spry1." (PMID 24932220, 2014).
ovarian carcinoma (continued). "Also, our results showing the difference in subcellular localization between Spry1 and Spry2 isoforms might be of functional significance in ovarian cancer." (PMID 23251157, 2012). "In ovarian cancer, SPRY4 expression levels are also down-regulated, while the changes in SPRY1 expression remain controversial." (PMID 27835572, 2016). "Our previous study revealed that human ovarian cancer cell lines, including SKOV-3 and 1A9, differentially express Spry1." (PMID 24932220, 2014). "On this basis, we postulated that the cellular content of the Spry1 protein, a known downstream regulator of RTK, could be a determinant of the ovarian cancer cell behavior." (PMID 24932220, 2014).
renal fibrosis (5 papers, 2020 to 2023). A final common manifestation of a wide variety of chronic kidney diseases characterized by glomerulosclerosis and tubulointerstitial fibrosis. "We revealed that m6A‐dependent pri‐miR‐21 processing promoted miR‐21‐5p expression and impacted obstructive renal fibrosis by activating the SPRY1/ERK/NF‐κB pathway." (PMID 34164910, 2021). "For animal experiments, the results revealed that melatonin remarkably ameliorated UUO‐induced renal fibrosis, attenuated the expression of miR‐21‐5p and pro‐fibrotic proteins and elevated Spry1 and PTEN expression." (PMID 32243691, 2020). "Additionally, studies have reported that SPRY1 was expressed in fibroblasts and affected several signaling cascades that regulate renal fibrosis." (PMID 32634115, 2020). "Moreover, SPRY1 is expressed in fibroblasts and affects several signaling cascades that regulate renal fibrosis and biological process." (PMID 32634115, 2020). "METTL3 facilitates miR-21-5p maturation, and miR-21-5p activates ERK/NF-κB signaling by suppressing sprouty RTK signaling antagonist 1 (SPRY1), which affects renal fibrosis progression." (PMID 37671161, 2023). "Our research is the first to demonstrate the role of the METTL3‐m6A‐miR‐21‐5p‐SPRY1/ERK/NF‐kB axis in obstructive renal fibrosis and provides a deeper understanding of renal fibrosis." (PMID 34164910, 2021). "We demonstrated that increased miR‐21‐5p levels induced by ureteral obstruction enhanced inflammation of the renal parenchyma by targeting SPRY1 and activating the ERK/NF‐kB pathway, which resulted in extracellular matrix (ECM) deposition and progression of obstructive renal fibrosis." (PMID 34164910, 2021). "Thus, our data indicate that the increased miR‐21‐5p level promoted inflammation in obstructive nephropathy by activating the SPRY1/ERK/NF‐kB signalling pathway and contributed to obstructive renal fibrosis development." (PMID 34164910, 2021). "As a consequence, our present exploration revealed that melatonin could ameliorate renal FMT and renal fibrosis via miR‐21‐5p/PTEN and/or miR‐21‐5p/Spry1 signalling pathway, which may be a vital anti‐fibrotic mechanism of melatonin." (PMID 32243691, 2020).
gastric cancer (4 papers, 2021 to 2025). A primary or metastatic malignant neoplasm involving the stomach. "This suppresses the expression of CDKN1B and SPRY1 along with their tumor-suppressive activities, thus promoting gastric cancer cell proliferation." (PMID 36010595, 2022). "The LncRNA UCA1, which is upregulated in gastric cancers, recruits EZH2 (enhancer of zeste homolog 2) to the promoters of the genes that encode p27 (CDKN1B) and the sprouty RTK signaling antagonist 1 (SPRY1) to mediate the repressive H3K27me3-trimethylation." (PMID 36010595, 2022). "A similar phenomenon occurs in gastric cancer with lncRNA urothelial cancer-associated 1 (UCA1) which binds to EZH2 and induces the down-regulation of tumor-suppressor factors including p21 and Sprouty RTK signaling antagonist 1 (SPRY1)." (PMID 35236381, 2022). "For instance, lncRNA UCA1 mediates the expression of p21 and SPRY1 through interacting with EZH2, thus facilitating tumour progression of gastric cancer." (PMID 33834618, 2021).
glioblastoma (4 papers, 2018 to 2022). The most malignant astrocytic tumor (WHO grade IV). "In particular, it had been previously shown that high expression of genes FREM2 (FRAS1 Related Extracellular Matrix 2) and SPRY1 (Sprouty RTK Signaling Antagonist 1) is specific to glioblastomas." (PMID 36613601, 2022). "A possible role for the SPRY1 gene in the pathology of glioblastoma has been addressed in multiple cases, as well as in our study, but unfortunately without any clear answers." (PMID 31357584, 2019). "In this study, we explored the roles of the FREM2 and SPRY1 genes and their proteins in glioblastoma pathology using human tissue samples." (PMID 31357584, 2019). "As such, for the first time, we deeply examined the relationships between both the FREM2 and SPRY1 genes and their proteins in glioblastoma." (PMID 31357584, 2019). "The role of SPRY1 in glioblastoma cell lines was also examined and it was shown that SPRY1 knock-down reduced expression of mesenchymal markers and impaired invasiveness of U251 cells." (PMID 31357584, 2019). "The study was based on previous data where we presented differential expression levels of the FREM2 and SPRY1 genes and their proteins in different glioblastoma cells, compared to astrocytes." (PMID 31357584, 2019). "In addition, the FREM2 and SPRY1 proteins show specific localization on the surface of glioblastoma cells." (PMID 31357584, 2019). "In addition, SPRY1 is one of the predicted targets of miR-21, which is over-expressed in glioblastoma-initiating cells." (PMID 31357584, 2019). "Previously, we identified FREM2 and SPRY1 as genes with differential expression in glioblastoma cell lines compared to nonmalignant astrocytes." (PMID 31357584, 2019). "In our previous study, we carried out a meta-analysis of the data from publicly available repositories, whereby we selected two genes that show selectivity towards glioblastoma: those for FRAS1-related extracellular matrix protein 2, FREM2, and sprouty RTK signaling antagonist 1, SPRY1." (PMID 31357584, 2019). "This validation revealed that the expression of FREM2—but not SPRY1—is higher in glioblastoma cell lines when compared to non-malignant astrocytes." (PMID 29734672, 2018). "In conclusion, we identified two new cell-surface glioblastoma marker candidates, FREM2 and SPRY1." (PMID 29734672, 2018).
heart failure (4 papers, 2010 to 2023). Inability of the heart to pump blood at an adequate rate to meet tissue metabolic requirements. "In a transgenic mouse model of cardiac failure, the elevated expression level of miR-21 induced fibrosis, hypertrophy, and cardiac dysfunction, by inhibiting SPRY1, which promoted ERK–MAPK signaling and cardiac fibroblast survival." (PMID 35118144, 2021). "In the stressed myocardium, mir-21 is significantly upregulated in cardiac fibroblasts and is responsible for fibroblast growth factor secretion as well as for the extent of interstitial fibrosis in heart failure via its effect on its target gene, Spry1." (PMID 20546595, 2010). "Overexpression of MiR-21 in heart failure modulates the activation of extracellular signal-regulated kinase mitogen-activated protein kinase (ERK-MAPK) by inhibiting sprouty protein homolog 1 (SPRY1)." (PMID 37306727, 2023). "miRNA-21 expression is increased in fibroblasts of heart failure, activating ERK-MAP kinase through inhibition of sprouty homologue 1 (Spry1)." (PMID 32922944, 2020).
lung carcinoma (4 papers, 2017 to 2021). "CD103+ TRM, both in tumor and non-tumor tissue, are marked by expression of PDCD1, ITGAE, CXCR6, and SPRY1 in lung cancer." (PMID 32471032, 2020). "Like Spry1 in lung cancer cells, Spry3 protein levels fail to fluctuate in response to serum-withdrawal in brain cancer-derived cells." (PMID 31374860, 2019). "In lung cancer derived cells, Spry1 levels were unaffected by mitogens." (PMID 34769378, 2021). "This microRNA is capable of promoting lung cancer by subexpressing several regulators (SPRED1, SPRED2, SPRY1, RASA1, SPRY3 and SPRY4) in RAS / MAPK signaling, which leads to an increase in the signaling of this pathway." (PMID 29053755, 2017). "Similarly, expression of SPRY1 and NR4A3 has been observed in CD103+ TRM in lung cancer." (PMID 32471032, 2020).
Obesity (4 papers, 2021 to 2025). Accumulation of substantial excess body fat. "Loss of SPRY1 has been associated with metabolic disorders, such as metabolic syndrome, diabetes, and obesity, with a phenotype characterized by excessive adipogenesis and reduced bone mass." (PMID 40694426, 2025). "Gonadal WAT fibrosis due to Spry1 deficiency is of particular interest because a recent study showed that 4 SNPs had a significant association with obesity-related traits and osteoporosis in humans." (PMID 34714716, 2021). "New interventions targeting LEP, NOTCH1, SPRY1, PPARG, ID2, and CIDEA gene network, in addition to what already is going on, can be designed for treatment and prevention of both obesity and tumors." (PMID 35395810, 2022).
osteosarcoma (4 papers, 2013 to 2021). A usually aggressive malignant bone-forming mesenchymal neoplasm, predominantly affecting adolescents and young adults. "In the following experiments we characterized six osteosarcoma-derived cell lines concerning their relative expression levels of Spry3 and Spry1 and evaluated how mitogen availability is influencing these expression levels." (PMID 34769378, 2021). "U2OS cells express hardly detectable amounts of Spry1, while the Spry3 amounts are more pronounced than in the most other osteosarcoma-derived cell lines, but about five times less than in SAOS2 cells." (PMID 34769378, 2021). "Along with the observations concerning Spry1, the herein presented data clearly demonstrate that Spry3 fulfills a tumor promoting function in osteosarcoma." (PMID 34769378, 2021). "All osteosarcoma-derived cell lines express Spry3 and Spry1, but wide variations were detected." (PMID 34769378, 2021). "Therefore, we first evaluated if elevated Spry1 and Spry3 levels are able to influence the cell proliferation of osteosarcoma-derived cells." (PMID 34769378, 2021). "Therefore, we investigated how ectopic Spry3 and Spry1 expressions influence the velocity of gap closure in a Scratch assay using osteosarcoma-derived cells." (PMID 34769378, 2021). "In contrast to U2OS cells, which express rather high Spry3 and low Spry1 levels, MG63 is the osteosarcoma-derived cell line with the highest Spry1 levels and has rather low Spry3 levels." (PMID 34769378, 2021). "Increased expression of Spry1 fails to influence the tested biological processes connected to malignancy of osteosarcoma." (PMID 34769378, 2021). "In summary the reported data demonstrate that Spry1 expression fails to significantly influence the proliferation, migration, and colony forming capacity of osteosarcoma, while increased Sprouty3 expression is beneficial for osteosarcoma in order to execute the malignant phenotype." (PMID 34769378, 2021).
cardiac hypertrophy (3 papers, 2021 to 2024). "In failing hearts, miR-21 increases in fibroblasts, boosting ERK–MAP kinase activity by inhibiting Spry1, which controls fibroblast survival, growth factor secretion, interstitial fibrosis, and cardiac hypertrophy." (PMID 39063038, 2024). "Elevated levels of miR-21 in cardiofibroblasts activate the MAPK signaling pathway by inhibiting the sprouty homolog 1 (SPRY1) protein, which promotes cardiac remodeling and cardiac hypertrophy." (PMID 38132140, 2023). "MiR-21 also regulates the activity of extracellular signal-regulated kinases (ERK)/MAPK in cardiac fibroblasts by SPRY1 controlling cardiac hypertrophy that could have contributed with the cardiac fibroblasts." (PMID 33804922, 2021).
colon carcinoma (3 papers, 2010 to 2016). "We raised the question whether suppression of SPRY1 in colon cancer cells would exhibit a diverse effect on E-cadherin expression." (PMID 26434583, 2016). "In addition, we demonstrated the positive SPRY1 regulation in a chimeric mouse model of human colon carcinoma in which 16 K hPRL treatment was shown to delay tumor growth." (PMID 20813052, 2010). "We evaluated relative expression of SPRY1 and SPRY2 mRNA transcripts in human colon cancer tissues and adjacent controls by utilizing a colon cancer cDNA array." (PMID 26434583, 2016). "Concurrent downregulation of SPRY1 and SPRY2 also increased E-cadherin and suppressed mesenchymal markers in colon cancer cells." (PMID 26434583, 2016). "Collectively, data indicate that suppression of both SPRY1 and SPRY2 had additional effects that favor epithelial phenotype in colon cancer cells." (PMID 26434583, 2016). "We established that concurrent suppression of SPRY1 and SPRY2 may have additional effects in decreasing EMT markers or EMT-inducing transcription factors and thus favoring epithelial phenotype in colon cancer cells." (PMID 26434583, 2016). "We further raised the question whether suppression of both SPRY1 and SPRY2 in colon cancer cells would exhibit a diverse effect on mesenchymal/EMT markers." (PMID 26434583, 2016).
fibrosis (3 papers, 2017 to 2024). the formation of excess fibrous connective tissue in an organ or tissue in a reparative or reactive process. "It has been previously shown that miR-21 is negatively associated with SPRY1 in the pro-fibrotic pathway and enhanced cardiac fibrosis via CADM1/STAT3 pathway in a model of rat cardiac fibroblasts." (PMID 33804922, 2021). "For example, miR-21 represses sprouty RTK signaling antagonist 1 (SPRY1) and promotes cardiac fibrosis through the transcription factor signal transducer and activator of transcription 3 (STAT3) signaling pathway in rats." (PMID 38338950, 2024). "In this study, we have demonstrated that AngII-upregulated mir-21 activates the NLRP3 inflammasome by targeting Spry1, which promoted lung fibroblast collagen synthesis and exacerbated BLM-induced fibrosis." (PMID 29084974, 2017).
Myocardial fibrosis (3 papers, 2018 to 2025). "By targeting SPRY1 protein, miR-21 leads to an increased expression of the mitogen-activated protein kinase (MAPK), which results in myocardial fibrosis and cardiac remodeling." (PMID 31671621, 2019). "In myocardial tissues, miR-21 targets endogenous mitogen activated protease inhibitor Spry1 and activates the ERK-MAPK pathway, thus inhibiting apoptosis of CFs and activating myocardial fibrosis." (PMID 30648109, 2018).